BDNF (brain derived neurotrophic factor)
Diseases named in the same sentence as BDNF in open-access papers (continued):
Sharing a sentence is not in itself a finding about the gene and the disease.
schizophrenia (continued). "Relationship between metabolites of the Kyn pathway and cytokines, hsCRP, and BDNF in the schizophrenia group." (PMID 34393855, 2021). "In the present study, we investigated the influence of repeated co-treatment with escitalopram and aripiprazole on the schizophrenia-like behavior and BDNF mRNA expression in adult rats exposed to glutathione deficit during early postnatal development." (PMID 34398437, 2021). "The interaction between antipsychotics binding on dopamine receptors, tDCS-induced dopamine release, and endogenous levels of BDNF needs further investigation in patients with schizophrenia." (PMID 34069556, 2021). "It has been shown that the level of BDNF is markedly reduced both in the plasma and post-mortem brains of patients suffering from schizophrenia, what suggests that BDNF dysfunction plays an important role in the pathogenesis of this disease." (PMID 34398437, 2021). "Brain Derived Neurotrophic Factor (BDNF) is the most widely distributed neurotrophin in the brain and it has been associated with several psychiatric disorders, including schizophrenia and other psychotic disorders." (PMID 34220575, 2021). "All of this suggests that changes in peripheral BDNF relate to changes in CNS functions in schizophrenia, having an impact on cognition as shown in this review." (PMID 34220575, 2021). "More unique finding of our study is that add-on neurofeedback—and not just any active treatment or standard rehabilitation—has a specific effect on increasing BDNF level and clinical improvement in schizophrenia." (PMID 34434228, 2021). "Brain-derived neurotrophic factor (BDNF) increased following treatment in schizophrenia (Hedges' g (g): 0.55; 95% confidence interval (CI) 0.39–0.70; p < 0.001) and MDD (g: 0.51; CI 0.06–0.96; p = 0.027)." (PMID 33653423, 2021). "There is also evidence of DNA hypomethylation in fragments of BDNF IV in patients who have schizophrenia compared to controls." (PMID 34970165, 2021). "The use of APDs has been shown to alter BDNF levels in the brain, cerebrospinal fluid (CSF), and serum in patients with schizophrenia, as reflected in animal studies." (PMID 35047549, 2021). "Studies of galvanic skin response biofeedback training in schizophrenia patients have also found a statistically significant increase in BDNF serum levels after a 3-month follow-up period." (PMID 34220575, 2021). "In a meta-analysis, Lin show that peripheral BDNF levels are inconsistently affected by antipsychotics in patients with schizophrenia, supporting that the role of BDNF in APD-induced weight gain is complex." (PMID 35047549, 2021). "We found that most of current research regarding BDNF and cognitive symptoms in psychosis is done around schizophrenia as a disease." (PMID 34220575, 2021). "Such aberrant alterations in circuit maturation and BDNF/TrkB signalling are profoundly evident in neurodevelopmental disorders including autism spectrum disorders (ASDs) and schizophrenia." (PMID 34360710, 2021). "The results of PA interventions in schizophrenia or related disorders also seem to be positive, with an increase of BDNF concentrations (n = 1)." (PMID 34445512, 2021). "Upregulation of H3K9me2 marks has been observed in schizophrenia biomarker genes, such as Glutamic acid decarboxylase, Brain-derived neurotrophic factor (BDNF) and Reelin." (PMID 34440561, 2021). "Due to the role played by BDNF in neurogenesis and synaptogenesis and its effect on the function of dopaminergic neurons, it can be used as a biomarker of schizophrenia and its treatment." (PMID 35194435, 2021). "Here, we used BDNF-haploinsufficient (BDNF+/−) mice to investigate the role of BDNF in different mouse behavioral endophenotypes of schizophrenia." (PMID 33888685, 2021). "Genetically-predicted BDNF (OR=0.97; 95% C.I., 0.94-1.00) and MCP-1 (OR=0.96; 95% C.I., 0.91-0.99) were associated with reduced schizophrenia risk." (PMID 34280516, 2021).
schizophrenia (continued). "The serum levels of Kyn and its metabolites, proinflammatory cytokines, and BDNF were measured in patients with schizophrenia and healthy controls." (PMID 34393855, 2021). "The aim of this study was to investigate the relationships of the Kyn pathway with proinflammatory cytokines, BDNF, and psychiatric symptoms in patients with schizophrenia." (PMID 34393855, 2021). "In another model of schizophrenia, a decrease in the level of BDNF mRNA in the prefrontal cortex and the hippocampus was observed." (PMID 34398437, 2021). "Studies have reported a differential methylation of the BDNF gene between patients with schizophrenia compared with controls." (PMID 34831111, 2021). "Some neuropathological features of schizophrenia are correlated with reduced levels of brain-derived neurotrophic factor (BDNF)." (PMID 33888685, 2021). "They found higher BDNF levels in patients with chronic schizophrenia, intermediate levels in patients with a first psychotic episode, and lower levels in ARMS." (PMID 34220575, 2021). "In this meta-analysis, we found evidence that growth factor BDNF increase and immune factor TNFα decrease following treatment in drug-naïve first-episode patients with either schizophrenia or MDD." (PMID 33653423, 2021). "We focused on male mice since in some human studies a more important role of BDNF in schizophrenia was found in male patients." (PMID 33888685, 2021). "While serum BDNF levels were found to be low in most studies of schizophrenia, a few studies have revealed high serum BDNF levels." (PMID 34763683, 2021). "A very useful animal model to investigate the role of BDNF in behavioral endophenotypes of schizophrenia is the BDNF-haploinsufficient (BDNF+/−) mouse strain that has an ~50% reduction in BDNF expression." (PMID 33888685, 2021). "BDNF and TNFα are possibly shared markers of an active first-episode of schizophrenia and MDD, since these blood compounds tend to normalize following treatment." (PMID 33653423, 2021). "As the BDNF protein level is already low in schizophrenia, the elevated miR-195 is unlikely due to a simple feedback mechanism by over-supplies of the BDNF protein." (PMID 33558459, 2021). "Studies in the literature have found a relationship between schizophrenia and BDNF in terms of cognitive functions, but this relationship was not confirmed in the current study." (PMID 34763683, 2021). "The postmortem brains of schizophrenia patients show decreased levels of BDNF and TrkB receptor mRNA and proteins, particularly in the PFC and hippocampus." (PMID 34445065, 2021). "There is also another important mechanism related to the pathophysiology of schizophrenia in which BDNF is involved in—glutamatergic neurotransmission." (PMID 32153434, 2020). "66Met carriers with schizophrenia spectrum or bipolar disorders exposed to childhood sexual abuse show reduced grey matter volumes, consistent with the reduced BDNF mRNA levels in 66Met carriers who were exposed to childhood sexual abuse." (PMID 32719625, 2020). "In a previous study, we measured serum brain derived neurotrophic factor (BDNF) in 160 schizophrenia patients between the ages of 16 and 65 before and after treatment with antipsychotic agents and ECT, and we found that both treatments increased serum BDNF." (PMID 32194452, 2020). "In summary, RSV showed a neuroprotective effect in the MK-801-induced schizophrenia rat model through activating the SIRT1/CREB/BDNF signaling pathway in the hippocampus." (PMID 32793005, 2020). "Both cerebral myelination and BDNF play important roles in the pathology and neurodevelopment of schizophrenia." (PMID 32973585, 2020). "Many studies have examined BDNF levels in schizophrenia and revealed that BDNF influences the therapeutic mechanisms of ECT." (PMID 32194452, 2020). "The TrkB gene is a high-affinity receptor of the BDNF that is changed in schizophrenia and mood disorders." (PMID 32351633, 2020).
schizophrenia (continued). "The SLF is a central fiber tract connecting the frontal, temporal, occipital, and parietal lobe and has an impact in memory and spatial information processing, functions that are impaired in schizophrenia and are also connected to BDNF." (PMID 32153434, 2020). "Several different studies have reported the correlation between the pathogenesis of schizophrenia and the abnormal expression of BDNF." (PMID 32793005, 2020). "Low serum BDNF levels have been reported among schizophrenia and in suicidal subjects, while SSRIs, mood stabilizers, and electroconvulsive therapy correlate with higher BDNF levels." (PMID 33152026, 2020). "For example, the BDNF epigenetic profile of prenatally stressed mice has shown similar epigenetic signatures as the post-mortem brain tissues of human patients with schizophrenia." (PMID 32509442, 2020). "The serum levels of BDNF in first-episode schizophrenia patients increased after a 12-week paliperidone treatment negatively correlated with a reduction rate of the positive and negative symptoms scale (PANSS) score (unspecified dose)." (PMID 32373066, 2020). "A BDNF dysfunction in schizophrenia either at a protein or an mRNA level has been strongly documented." (PMID 32351633, 2020). "The upregulated BDNF then tries to induce plasticity by activating its TrkB pathway, but as mentioned in literature, this signaling cascade is believed to be altered in patients with schizophrenia so that BDNF cannot induce its effects of plasticity anymore." (PMID 32153434, 2020). "Our pilot study was one of the first to explore potential correlations between BDNF serum levels and meso- and macroscopic imaging parameters in schizophrenia patients." (PMID 32153434, 2020). "We investigated a possible correlation between BDNF serum levels, fiber tract architecture, and regional grey matter volumes in 19 schizophrenia patients and a gender- and age-matched control group." (PMID 32153434, 2020). "Some studies also described significant relationships between oxidative stress parameters and BDNF in individuals with BD and schizophrenia." (PMID 33061913, 2020). "In particular, meta-analyses showed a reduction of BDNF serum levels in schizophrenia with moderate effect sizes and heterogeneity." (PMID 32153434, 2020). "Data showed that not only the BDNF but also its receptor, TrkB, are changed in patients with schizophrenia." (PMID 32351633, 2020). "The levels of BDNF has also been correlated with the intensity of the psychopathological symptoms in patients with schizophrenia." (PMID 32351633, 2020). "Some literatures reported that the levels of BDNF and TrkB receptor mRNA in prefrontal cortex and hippocampus of patients with chronic schizophrenia were significantly decreased." (PMID 31420036, 2019). "Second, we did not analyze the influence of inflammation on the correlation between BDNF and schizophrenia." (PMID 31420036, 2019). "Associations of low BDNF with psychotic-affective disorders are also supported by (i) a negative correlation of BDNF levels with psychotic symptoms of schizophrenia and (ii) increased BDNF after treatment with antipsychotic and antidepressant drugs." (PMID 31548888, 2019). "BDNF aberrancies have been observed in schizophrenia and ASD, suggesting a contribution of abnormal HERV activity in the BDNF-mediated neuroprotective mechanism." (PMID 31616420, 2019). "In contrast, increased levels of serum BDNF have been observed after electroconvulsive and antipsychotic therapy in schizophrenia patients." (PMID 31098654, 2019). "BDNF levels in the hippocampus of rats with MK-801-induced schizophrenia (0.5 mg/kg daily for 6 days) were examined by immunohistochemistry and western blotting." (PMID 31396062, 2019). "Previous studies have shown that peripheral BDNF in patients with chronic or first-episode schizophrenia are decreased, while BDNF mRNA was reduced in the postmortem brain of patients." (PMID 31420036, 2019).
schizophrenia (continued). "This is the first RCT study that describes changes in peripheral BDNF levels in schizophrenia patients supplemented with PUFA." (PMID 31098654, 2019). "Many studies have suggested that BDNF plays an important role in the pathophysiology of schizophrenia." (PMID 31396062, 2019). "BDNF is also a candidate gene, with decreased levels found in both peripheral serum and brain from participants with schizophrenia." (PMID 31185023, 2019). "It is also thought that antipsychotics differentially affect serum or plasma BDNF protein levels according to the ethnic background of patients with schizophrenia." (PMID 31396062, 2019). "Most previous studies have shown decreased peripheral levels of BDNF in schizophrenia patients, as reflected in the meta-analyses." (PMID 31098654, 2019). "There is much evidence in literature describing a significant reduction in peripheral BDNF concentrations in patients with schizophrenia." (PMID 31614739, 2019). "According to a recent report, peripheral BDNF concentrations are significantly lower in schizophrenia patients than those in healthy subjects." (PMID 29896133, 2018). "In terms of neurocognitive-genetic investigations, catechol-O-methyltransferase (COMT) and brain-derived neurotrophic factor (BDNF) are the two most studied candidate genes especially in patients with schizophrenia." (PMID 30349492, 2018). "Post-mortem studies have reported reduced levels of BDNF and its cognate receptor, Tropomysosin-related kinase B (TrkB) in the prefrontal cortex (PFC) and hippocampus of individuals with schizophrenia, suggesting a role of BDNF-TrkB signaling in the illness." (PMID 30356704, 2018). "We investigated the relationship among the patients' age, psychotic severity, treatment medication, serum BDNF levels, and cognitive functioning (measured by the Japanese-language version of the Brief Assessment of Cognition in Schizophrenia; BACS-J)." (PMID 29896133, 2018). "Many studies showed that BDNF expression was reduced in persons with schizophrenia, but some studies showed the opposite result." (PMID 30233327, 2018). "A meta-analysis showed that the blood BDNF concentration in schizophrenia patients is lower than that in healthy controls." (PMID 29896133, 2018). "Serum brain-derived neurotrophic factor and clozapine daily dose in patients with schizophrenia: a positive correlation." (PMID 30093869, 2018). "BDNF is a neurotrophic factor and epigenetic changes of the BDNF gene are related to the pathophysiology of schizophrenia." (PMID 29991943, 2018). "The reduced expression of BDNF and increases in the promoter methylation of BDNF exons IV and IX have been identified in the frontal cortex and hippocampus of patients with schizophrenia." (PMID 29991943, 2018). "Considering these findings, we aim to identify the factor (i.e., psychotic severity, aging, medication, or BDNF) that has the greatest influence on cognitive functioning in patients with chronic schizophrenia." (PMID 29896133, 2018). "BDNF shapes the development of neuronal circuits, as well as the construction of inhibitory connections throughout life and alterations in BDNF processing have been observed in diseases of the CNS, including schizophrenia, ASD and epilepsy." (PMID 30210299, 2018). "Low plasma BDNF level has been associated with high plasma hcy level in drug naïve, first episode schizophrenia patients compared to healthy control group, which may play an important role in the neurodevelopmental process and clinical manifestation of schizophrenia." (PMID 30172984, 2018). "Another study in subjects with the schizophrenia spectrum or bipolar disorder demonstrated that Met carriers with high levels of childhood trauma have significantly low levels of blood BDNF mRNA and decreased CA2/3 and CA4 subfield areas in the dentate gyrus." (PMID 29867348, 2018).
schizophrenia (continued). "A specific BDNF SNP (single nucleotide polymorphism) and other BDNF haplotypes, linkage peaks and NTRK2 (TrkB) gene variations are associated with autism, bipolar disorder, schizophrenia, OCD and ADHD." (PMID 29691724, 2018). "Another study compared serum BDNF levels of 60patients with schizophrenia who were undergoing treatment with 26 healthy people and 30 euthymic patients who were bipolar." (PMID 29287075, 2017). "For example, when compared with healthy volunteers, a significant decrease was found in the serum BDNF levels of patients with schizophrenia.In contrast, other studies report increasing levels of BDNF in patients with schizophrenia." (PMID 29287075, 2017). "Studies of BDNF as a peripheral biomarker in psychiatric disorders, including schizophrenia, are supported by a strong positive correlation between peripheral BDNF levels and BDNF levels in the CNS." (PMID 28358316, 2017). "In post-mortem studies, a decrease in BDNF levels in frontal cortices and an increase in hippocampus have been reported in schizophrenia patients." (PMID 29321734, 2017). "Serum BDNF levels seem to be one of the indicators of schizophrenia and its progress; nevertheless, there is insufficient information about this neurotropic factor." (PMID 29287075, 2017). "That the drug-naïve duration of patients with schizophrenia is longer than Western countries facilitated an analysis between drug-naïve duration and serum BDNF levels." (PMID 29287075, 2017). "The results showed the serum BDNF levels of the group with schizophrenia were significantly higher than the control group." (PMID 29287075, 2017). "In early clinical studies, clozapine-treated schizophrenia patients showed higher serum BDNF levels than risperidone-treated patients." (PMID 29321734, 2017). "Future studies should focus on linking specific BDNF haplotype combinations with treatment response in patients with schizophrenia." (PMID 28358316, 2017). "Earlier studies found a gender difference of BDNF levels in patients with schizophrenia, and our finding continued to support this notion." (PMID 28562580, 2017). "Different epigenetic mechanisms are responsible for activity-dependent regulation of BDNF gene expression, implicating the possible role of the regulation of BDNF expression in several psychiatric disorders including schizophrenia." (PMID 28358316, 2017). "A significant correlation between serum BDNF levels and clozapine daily dose was found, suggesting also that the treatment with clozapine can lead to cognitive enhancement in patients with schizophrenia." (PMID 28358316, 2017). "Though there are limited amount of data derived from drug-naïve patients with schizophrenia in literature, it was detected that drug-naïve patients had lower BDNF levels compared with those of controls." (PMID 29287075, 2017). "44,45There is also some preliminary evidence supporting the role of BDNF as a mediating factor for cognitive improvements from exercise in schizophrenia." (PMID 27521348, 2017). "Most of the studies reported reduced expression of BDNF gene and significantly decreased BDNF protein concentration in different brain areas, and decreased concentration of plasma BDNF in patients with schizophrenia." (PMID 28358316, 2017). "The results indicated that the serum BDNF levels of patients with schizophrenia were significantly higher than that of both the bipolar group and the control group." (PMID 29287075, 2017). "Studies have shown significantly reduced expression of BDNF gene, gene coding for TrkB receptor, and significantly decreased BDNF protein concentration in the hippocampus of patients with schizophrenia." (PMID 28358316, 2017). "Decreased mRNA expression of BDNF, TrkB, and glutamic acid decarboxylase was also shown in the hippocampus of individuals with schizophrenia and mood disorders." (PMID 28466254, 2017).